GPATCH11 (G-patch domain containing 11)
Synonyms: CENP-Y; CCDC75; FLJ38348; CENPY
Gene: Protein-coding gene on chromosome 2 (37,084,482 to 37,099,244, forward strand). Ensembl gene ENSG00000152133.
Subcellular location: Chromosome, centromere, kinetochore
Subcellular location (Human Protein Atlas): Nucleoplasm
Genetic constraint (gnomAD): Loss-of-function variants: 15 observed, 22.91 expected, observed/expected ratio (o/e) 0.65, 90% interval 0.44 to 1.01. The upper end of that interval is the gene's LOEUF score, 1.01, which puts it in group 4 of 6, group 1 being the genes least tolerant of losing a copy. Missense variants: 175 observed, 172.1 expected, observed/expected ratio (o/e) 1.02, 90% interval 0.9 to 1.15. Synonymous variants: 48 observed, 55.44 expected, observed/expected ratio (o/e) 0.87, 90% interval 0.69 to 1.1.
Homologues: Orthologues: chimpanzee GPATCH11 (99% identical), pig GPATCH11 (94% identical), rabbit GPATCH11 (94% identical), dog GPATCH11 (92% identical), guinea pig GPATCH11 (92% identical), mouse Gpatch11 (90% identical), rat Gpatch11 (90% identical), macaque GPATCH11 (85% identical), zebrafish gpatch11 (56% identical), tropical clawed frog gpatch11 (55% identical), Drosophila melanogaster CG10053 (35% identical), Caenorhabditis elegans T04H1.5 (32% identical).
Diseases named in the same sentence as GPATCH11 in open-access papers:
GPATCH11 is named in the same sentence as 2 diseases in open-access papers, as found by Europe PMC text mining. Sharing a sentence is not in itself a finding about the gene and the disease.
GPATCH11 shares sentences with these, for which no sentence is quoted: colorectal cancer (1 paper); lung adenocarcinoma (1).